DCAF13 (DDB1 and CUL4 associated factor 13)
Description:
Part of the small subunit (SSU) processome, first precursor of the small eukaryotic ribosomal subunit. During the assembly of the SSU processome in the nucleolus, many ribosome biogenesis factors, an RNA chaperone and ribosomal proteins associate with the nascent pre-rRNA and work in concert to generate RNA folding, modifications, rearrangements and cleavage as well as targeted degradation of pre-ribosomal RNA by the RNA exosome. Participates in the 18S rRNA processing in growing oocytes, being essential for oocyte nonsurrounded nucleolus (NSN) to surrounded nucleolus (SN) transition. Substrate-recognition component of a DCX (DDB1-CUL4-X-box) E3 ubiquitin-protein ligase complex that plays a key role in embryo preimplantation and is required for normal meiotic cycle progression in oocytes. Acts as a maternal factor that regulates oocyte and zygotic chromatin tightness during maternal to zygotic transition (By similarity). Also involved in the transformation of the endometrium into the decidua, known as decidualization, providing a solid foundation for implantation of blastocysts. Recognizes the histone methyltransferases SUV39H1 and SUV39H2 and directs them to polyubiquitination and proteasomal degradation, which facilitates the H3K9me3 removal and early zygotic gene expression, essential steps for progressive genome reprogramming and the establishment of pluripotency during preimplantation embryonic development. Supports the spindle assembly and chromosome condensation during oocyte meiotic division by targeting the polyubiquitination and degradation of PTEN, a lipid phosphatase that inhibits PI3K pathway as well as oocyte growth and maturation. Targets PMP22 for polyubiquitination and proteasomal degradation (By similarity).
Synonyms: WDSOF1; HSPC064; DKFZP564O0463; Gm83; Sof1
Tractability: Small molecule: a structure with a bound ligand is known. PROTAC: ubiquitination databases record sites on it; its protein half-life has been measured.
Gene: Protein-coding gene on chromosome 8 (103,414,714 to 103,443,579, forward strand). Ensembl gene ENSG00000164934.
Subcellular location: Nucleus, nucleolus
Subcellular location (Human Protein Atlas): Nucleoli; Nucleoplasm; Cell Junctions; Centrosome; Cytosol
Pathways (Reactome):
Metabolism of RNA: Major pathway of rRNA processing in the nucleolus and cytosol; rRNA modification in the nucleus and cytosol
Metabolism of proteins: Neddylation
Gene Ontology:
Molecular function: nuclear estrogen receptor binding; protein binding; RNA binding; ubiquitin-like ligase-substrate adaptor activity
Biological process: decidualization; epigenetic programming in the zygotic pronuclei; proteasome-mediated ubiquitin-dependent protein catabolic process; spindle assembly involved in female meiosis; epigenetic regulation of gene expression; maturation of SSU-rRNA; maturation of SSU-rRNA from tricistronic rRNA transcript (SSU-rRNA, 5.8S rRNA, LSU-rRNA); oocyte growth; regulation of embryonic development; rRNA processing; female gamete generation; protein ubiquitination
Cellular component: Cul4-RING E3 ubiquitin ligase complex; nucleolus; Cul4A-RING E3 ubiquitin ligase complex; Cul4B-RING E3 ubiquitin ligase complex; nucleoplasm; small-subunit processome
Genetic constraint (gnomAD): Loss-of-function variants: 23 observed, 38.41 expected, observed/expected ratio (o/e) 0.6, 90% interval 0.43 to 0.85. The upper end of that interval is the gene's LOEUF score, 0.85, which puts it in group 3 of 6, group 1 being the genes least tolerant of losing a copy. Missense variants: 325 observed, 411.73 expected, observed/expected ratio (o/e) 0.79, 90% interval 0.72 to 0.87. Synonymous variants: 121 observed, 130.95 expected, observed/expected ratio (o/e) 0.92, 90% interval 0.8 to 1.08.
Homologues: Orthologues: chimpanzee DCAF13 (99% identical), macaque DCAF13 (98% identical), dog DCAF13 (97% identical), pig DCAF13 (96% identical), guinea pig DCAF13 (93% identical), mouse Dcaf13 (93% identical), rat Dcaf13 (93% identical), rabbit DCAF13 (91% identical), tropical clawed frog dcaf13 (80% identical), zebrafish dcaf13 (74% identical), Drosophila melanogaster CG7275 (59% identical), Caenorhabditis elegans dcaf-13 (47% identical).
Diseases named in the same sentence as DCAF13 in open-access papers:
DCAF13 is named in the same sentence as 20 diseases in open-access papers, as found by Europe PMC text mining. Sharing a sentence is not in itself a finding about the gene and the disease. The quoted sentences say what the papers report.
breast carcinoma (11 papers, 2007 to 2025). "In the present study, we report evidence that DCAF13 is aberrantly overexpressed in human breast cancer and its expression is positively associated with cancer progression." (PMID 34775691, 2022). "The result showed that high DCAF13 expression is associated with a poor overall survival probability in patients with breast cancer." (PMID 34775691, 2022). "In the present study, we report evidence showing that DCAF13 is aberrantly overexpressed in human breast cancer and its expression positively associates with cancer progression." (PMID 34775691, 2022). "Overexpression of DCAF13 has also been associated with cell migration and epithelial-mesenchymal transition in human breast cancer cells." (PMID 36217444, 2022). "In the present study, we report evidence revealing that DCAF13 is aberrantly overexpressed in human breast cancer and its expression positively associates with cancer progression." (PMID 34775691, 2022). "Overexpression of DCAF13 was associated with significantly worse prognosis in patients diagnosed with a subgroup of breast cancers hepatocellular carcinoma, and lung carcinoma." (PMID 36217444, 2022). "Two other studies also showed that DCAF13 was increased in hepatocellular carcinoma or breast cancer, and obviously associated with poor overall survival." (PMID 32071816, 2020). "DCAF13 may serve as a therapeutic target for reducing the risk of breast cancer metastasis, especially for patients undergoing doxorubicin chemotherapy." (PMID 34775691, 2022). "Future therapeutics targeting DCAF13 may help reduce the risk of breast cancer metastasis, especially for patients undergoing chemotherapy." (PMID 34775691, 2022). "Next, we attempted to explore the cellular processes that are regulated by DCAF13 in human breast cancer." (PMID 34775691, 2022). "We also investigated the regulatory role of DCAF13 in cell proliferation, cell cycle progression and apoptosis of breast cancer cells." (PMID 34775691, 2022). "In present study, we report evidence demonstrating that doxorubicin treatment promotes breast cancer cell migration and invasion by upregulating DCAF13." (PMID 34775691, 2022). "The epithelial cell marker β‐catenin was upregulated, whereas the mesenchymal cell marker fibronectin was downregulated upon DCAF13 knockdown, suggesting that DCAF13 promotes EMT in human breast cancer." (PMID 34775691, 2022). "A wound healing assay was carried out to assess the change in breast cancer cell migration ability upon DCAF13 knockdown." (PMID 34775691, 2022). "DCAF13 has been reported to function as an oncogenic E3 ligase in breast cancer and osteosarcoma by the targeting and degradation of tumor suppressors PERP and PTEN, respectively." (PMID 36359803, 2022). "Again, this effect was also mediated by DCAF13 because DCAF13 silencing suppressed doxorubicin‐induced EMT of breast cancer cells." (PMID 34775691, 2022). "To this end, we split the breast cancer samples into DCAF13‐high and DCAF13‐low groups based on the median DCAF13 expression level." (PMID 34775691, 2022). "Taken together, our results demonstrate a promoting role of DCAF13 in the EMT process of human breast cancer cells." (PMID 34775691, 2022). "The result showed that doxorubicin treatment dramatically increased DCAF13 expression in breast cancer cells." (PMID 34775691, 2022). "The finding of EMT gene set enrichment prompted us to further explore the regulatory role of DCAF13 in the EMT of breast cancer cells." (PMID 34775691, 2022). "Given the fact that EMT is closely associated with cancer cell invasiveness and cancer metastasis, we next investigated the impact of DCAF13 knockdown on breast cancer cell migration and invasion." (PMID 34775691, 2022).
breast carcinoma (continued). "To evaluate the prognostic value of DCAF13 expression in human breast cancer, we performed a log‐rank test to assess the difference between the survival curves of the DCAF13_high group and the DCAF13_low group." (PMID 34775691, 2022). "Taken together, our results demonstrate that DCAF13 promotes the epithelial–mesenchymal transition in human breast cancer cells, indicating an involvement in breast cancer metastasis." (PMID 34775691, 2022). "The results of western blotting and immunofluorescence staining assays demonstrate that DCAF13 promotes EMT in human breast cancer." (PMID 34775691, 2022). "The results showed that DCAF13 expression was aberrantly upregulated in breast cancer samples compared to normal breast tissue samples." (PMID 34775691, 2022). "We also carried out a transwell cell invasion assay to examine the effect of DCAF13 knockdown on breast cancer cell invasion ability." (PMID 34775691, 2022). "Previous studies have shown that DCAF13 is amplified in various tumors, such as hepatocellular carcinoma, breast cancer, and osteosarcoma." (PMID 32071816, 2020). "To further investigate whether the upregulation of DCAF13 by doxorubicin treatment may lead to enhanced breast cancer metastasis, we performed wound healing and transwell cell invasion assays." (PMID 34775691, 2022). "By analyzing the RNA‐sequencing data, we found that DCAF13 might regulate EMT in human breast cancer." (PMID 34775691, 2022). "Further screenings for DCAF13 substrates in breast cancer are needed in this regard." (PMID 34775691, 2022). "Alternatively, DCAF13 may function as a RBP targeting the mRNAs of crucial EMT repressors for degradation to promote EMT in breast cancer." (PMID 34775691, 2022). "DCAF13 knockdown dramatically reduced the migration ability of breast cancer cells." (PMID 34775691, 2022). "In the present study, we show that DCAF13 is aberrantly overexpressed in human breast cancer." (PMID 34775691, 2022). "Furthermore, we report that doxorubicin, a widely used chemotherapy drug, increases DCAF13 expression in breast cancer cells, leading to enhanced cancer cell migration and invasion." (PMID 34775691, 2022). "Similarly, DCAF13 has also been found to be highly expressed in a variety of tumors, including breast cancer, leading to a poorer tumor prognosis." (PMID 33195699, 2020). "Although the function of DCAF13 has not yet been demonstrated, findings indicate that DCAF13 is associated with worse prognosis of breast cancer patients and HCC patients, which is consistent with our finding." (PMID 30918751, 2019). "DCAF13, located in chromosome 8q22.3, has been shown to be amplified in breast cancer." (PMID 32010179, 2019). "To this end, we first knocked down DCAF13 expression in breast cancer cell lines, BT549 and MDA‐MB‐231, and then examined the effect of DCAF13 knockdown on EMT gene expression." (PMID 34775691, 2022). "We also split the breast cancer samples into TNBC and non‐TNBC groups and analyzed DCAF13 expression separately in both groups, as well as in normal breast tissue samples." (PMID 34775691, 2022). "Together, these results demonstrate that DCAF13 regulates EMT gene expression in breast cancer and thus regulates breast cancer metastasis." (PMID 34775691, 2022). "Further analysis showed that DCAF13 expression level is significantly higher in TNBC compared to non‐TNBC, indicating its positive correlation with breast cancer aggressiveness." (PMID 34775691, 2022). "Our results also demonstrate that DCAF13 and SKP2 play essential roles in breast cancer prognosis." (PMID 39781342, 2025).
breast carcinoma (continued). "Although, in the present study, we demonstrate that DCAF13 promotes EMT in breast cancer and thus promotes metastasis, we do not yet know what substrates of DCAF13 are involved in this process." (PMID 34775691, 2022). "Subsequent studies revealed that DCAF13 regulates cancer cell migration, invasion and epithelial–mesenchymal transition in human breast cancer, whereas it has no significant impact on breast cancer cell proliferation, cell cycle progressionor apoptosis." (PMID 34775691, 2022). "Further analysis demonstrates that DCAF13 promotes EMT in human breast cancer cells, whereas it has no regulatory roles in breast cell proliferation, cell cycle progression and apoptosis." (PMID 34775691, 2022). "The survival analysis suggested that DCAF13, EZR, MRPL13, APOBEC3C, and EIF4E3 might have a prognostic value for breast cancer." (PMID 30881302, 2019). "However, DCAF13 does not regulate breast cancer cell proliferation, cell cycle progression and apoptosis." (PMID 34775691, 2022). "We did not observe any significant impact of DCAF13 silencing on breast cell proliferation, cell cycle progression and apoptosis, suggesting that DCAF13 may not regulate primary tumor growth of breast cancer." (PMID 34775691, 2022). "Interestingly, DCAF13 expression level was significantly higher in TNBC samples compared to non‐TNBC samples, suggesting a positive correlation between DCAF13 expression and breast cancer aggressiveness." (PMID 34775691, 2022). "Further analysis showed that the DCAF13 expression level is significantly higher in triple‐negative breast cancer compared to non‐triple‐negative breast cancer, indicating a positive correlation between its expression and the aggressiveness of breast cancer." (PMID 34775691, 2022).
hepatocellular carcinoma (3 papers, 2019 to 2022). A malignant tumor that arises from hepatocytes. "DCAF13 expression is positively correlated with advanced hepatocellular carcinoma grade and closely associated with poorer survival." (PMID 34775691, 2022). "The DCAF13 gene was also found to be amplified in 14.7% of cases of hepatocellular carcinoma and its expression was upregulated in hepatocellular carcinoma." (PMID 34775691, 2022). "Besides hepatocellular carcinoma, DCAF13 was also shown to be of prognostic value in lung adenocarcinoma." (PMID 34775691, 2022). "Studies have shown that overexpression of DCAF13 in hepatocellular carcinoma is significantly correlated with low survival and it may be involved in the regulation of cell cycle." (PMID 30881302, 2019).
lung adenocarcinoma (3 papers, 2020 to 2026). A carcinoma that arises from the lung and is characterized by the presence of malignant glandular epithelial cells. "In this study, we aimed to investigate the regulatory mechanisms of DCAF13 in lung adenocarcinoma (LUAD)." (PMID 38163876, 2024). "So as to investigate the effect of DCAF13 on lung adenocarcinoma cell function using in vivo and in vitro." (PMID 38163876, 2024). "Analysis of The Cancer Genome Atlas (TCGA) data revealed that seven DCAF genes (DCAF2, DCAF4, DCAF7, DCAF12, DCAF13, DCAF15, and DCAF17) were significantly upregulated in lung adenocarcinoma (LUAD)." (PMID 41047465, 2026).
lung carcinoma (2 papers, 2020 to 2024). "Similarly, Kaplan-Meier analysis from the KM-plotter database revealed that patients with high DCAF13 expression had a significantly worse survival than those with low DCAF13 mRNA expression in lung cancer (p = 3.6e-05)." (PMID 38163876, 2024). "DDB1 and CUL4 associated factor 13 (DCAF13) is a substrate receptor of the E3 ubiquitin ligase CRL4, but its role in lung cancer remains unknown." (PMID 38163876, 2024).
Infertility (1 paper, 2025). "To investigate its function, we generated Dcaf13 conditional knockout (cKO) mice and discovered that the uteri of cKO mice became smaller and thinner as they mature, and the embryos were unable to implant, leading to infertility." (PMID 40750792, 2025). "Consequently, a novel avenue for research is presented: investigating the functions of DCAF13 in the uterus, with a particular emphasis on the pathogenesis of infertility." (PMID 40750792, 2025).
invasive breast carcinoma (1 paper, 2019). A carcinoma that infiltrates the breast parenchyma. "Overexpression of DCAF13, DNMT3B, KPNA2, EXO1, FANCI, RACGAP1, and ZNF106 in invasive breast carcinoma patients showed poor survival, while overexpression of CDKN2A, SORBS1, and TP63 showed better survival." (PMID 32010179, 2019).
liver cancer (1 paper, 2020). An epithelial or non-epithelial malignant neoplasm that arises from the liver. "DCAF13 is upregulated in liver cancer and significantly related to poor survival." (PMID 32071816, 2020).
melanoma (1 paper, 2023). A malignant, usually aggressive tumor composed of atypical, neoplastic melanocytes. "Although PRDX6, MAGOHB, NUCKS1, DCAF13, and TXN genes as a panel displayed weak prediction of ICB response, the panel robustly stratified overall survival in patients with melanoma treated with anti-PD1 following progression on anti-CTLA4 therapy." (PMID 37835514, 2023).
oral carcinoma (1 paper, 2020). "A study revealed that NSUN2 gene copy number was elevated in colorectal and oral carcinoma.We also found that DCAF13 and BOP1 have high copy number gain frequency in patients with LUAD." (PMID 32071816, 2020).
ovarian carcinoma (1 paper, 2025). A malignant neoplasm originating from the surface ovarian epithelium. "Similarly, regulators of RNA processing and splicing such as TCEA1, SF3B6, ZCRB1, PNO1, and DCAF13 were overexpressed, indicating dysregulation of mRNA metabolism and splicing fidelity in ovarian cancer." (PMID 41228302, 2025).
Pancytopenia (1 paper, 2026). An abnormal reduction in numbers of all blood cell types (red blood cells, white blood cells, and platelets). "Conditional deletion of Dcaf13 in murine hematopoietic cells results in severe pancytopenia, rapid mortality, and complete HSC depletion in both fetal and adult hematopoietic compartments." (PMID 41787937, 2026).
premature ovarian failure (1 paper, 2024). "DCAF13 functions as a substrate recognizer in the CRL4 E3 ligase complex, and Dcaf13 deletion in the oocyte caused premature ovarian failure." (PMID 38578457, 2024).
triple-negative breast carcinoma (1 paper, 2023). An invasive breast carcinoma which is negative for expression of estrogen receptor (ER), progesterone receptor (PR), and human epidermal growth factor receptor 2 (HER2). "Recently, it was found that a high dose of DOX led to significant upregulation of the substrate receptor DCAF13 with an assumed metastasizing effect in the case of triple-negative breast cancer." (PMID 37511111, 2023).